BRCA1 (BRCA1 DNA repair associated)
Diseases named in the same sentence as BRCA1 in open-access papers (continued):
Sharing a sentence is not in itself a finding about the gene and the disease.
breast cancer (continued). "BRCA1-associated breast cancers are commonly poorly differentiated, have “medullary features” (a syncytial growth pattern with pushing margins and lymphocytic responses), and are biologically similar to the basal-like subtype defined by gene expression profiling." (PMID 34926274, 2021). "Our findings enhance the understanding of DNA damage and biomarker responses in BRCA1-associated mammary tumors and provide preclinical evidence that radiotherapy with synthetic DNA damage is a potential strategy for the therapeutic management of BRCA1-associated breast cancer." (PMID 33767581, 2021). "Of these, BRCA1 had the highest risk of breast cancer susceptibility (OR: 42.1, 95% CI: 26.8–66.2)." (PMID 34606182, 2021). "Also, data on the association of HRT use and breast cancer in BRCA1/2 mutation carriers are limited, especially for BRCA2 mutation carriers." (PMID 33885953, 2021). "PARP inhibitor olaparib is effective in treating breast cancer patients with BRCA1 mutations." (PMID 34131406, 2021). "Recent data had suggested that patients with advanced-stage breast cancer associated with BRCA1 or BRCA2 mutations may benefit from PARP (poly ADP ribose polymerase) inhibitors like olaparib and talazoparib; both are currently approved for such situation." (PMID 34290354, 2021). "Regarding breast cancer, in addition to the known high-penetrance pathogenic variants of BRCA1/2, mutations in other high- or intermediate-penetrance genes can increase the risk of cancer and the most common non-BRCA pathogenic or likely pathogenic variants affect PALB2, ATM, and CHEK2 genes." (PMID 33800556, 2021). "Germline pathogenic variants (PVs) in the BRCA1 or BRCA2 genes cause high breast cancer risk." (PMID 33573335, 2021). "Similarly, mammary tumors from BRCA1-deficient mice exhibited increased expression of Ang-1 together with notable vascular growth." (PMID 33540843, 2021). "Interestingly, SNORA68 is located at the p13.1 locus on chromosome 19 (19p13.1), a region previously associated with susceptibility to both ovarian and breast cancer in the population with BRCA1 or BRCA2 mutation carriers." (PMID 33125686, 2021). "Indeed, in breast cancer patients with variants such as in BRCA1, BRCA2, and ATM, it is recommended that the contralateral breast dose in mammography and radiotherapy be minimized in order to prevent secondary carcinogenesis." (PMID 34608183, 2021). "Genetic analysis results showed that 36 out of 354 tested breast and ovarian cancer patients were BRCA1/2 mutation carriers (31 breast cancer cases and 5 ovarian cancer patients), including 21 patients with BRCA1 mutation and 15 patients carrying BRCA2 mutation." (PMID 34490083, 2021). "Here, the authors demonstrate an aberrant differentiation of luminal progenitors towards a partial secretory luminal cell phenotype that occurs in a Brca1 deficient mouse model of breast cancer at early stages of tumour initiation and in breast cells from BRCA1 carriers." (PMID 33686070, 2021). "And loss of BRCA1 induces mammary tumors in a stochastic manner." (PMID 34815798, 2021). "In routine mammography exams, only 0.5% of the cases will have cancer present, however if the patient has the BRCA1 or BRCA2 genetic mutation (colloquially referred to as the “breast cancer gene”), there is a 82% chance of developing cancer during their lifetime." (PMID 33740159, 2021). "Carriers of pathogenic variants in BRCA1/2 may consider risk-reducing bilateral mastectomy to reduce cancer incidence by up to 95% and breast cancer-specific mortality by 80%." (PMID 33836815, 2021).
breast cancer (continued). "Several studies showed a strong correlation between specific BRCA1/2 variants and changes in BC/OC relative risk, by identifying specific putative Breast Cancer Cluster Regions (BCCRs) and Ovarian Cancer Cluster Regions (OCCRs) located on the coding DNA sequences of BRCA1/2 genes." (PMID 34178674, 2021). "Our findings may help to explain why obesity increases the risk of early-onset breast cancer in BRCA1/2 mutation carriers, including those who are pre-menopausal." (PMID 33649363, 2021). "In addition, 8–17% of OC are associated with BRCA1/2 variations, whereas 51-54% are associated with breast cancer." (PMID 34064977, 2021). "In this study we investigated the associations between an established PRS based on 313 variants for primary first breast cancer and contralateral breast cancer risks among BRCA1 and BRCA2 heterozygotes of European ancestry enrolled in the large international retrospective CIMBA cohort." (PMID 34113011, 2021). "Patients who carry a germline pathogenic mutation in BRCA1/2 genes have a significantly increased risk of developing breast cancer and might benefit from targeted therapy." (PMID 34354733, 2021). "However, breast cancer patients with BRCA1/2 mutations tend to acquire triple-negative tumors that are not susceptible to newly popular hormone receptor targeting." (PMID 34070674, 2021). "Somatic mutations in BRCA1/2 are uncommon in primary ER+ breast cancer." (PMID 34524841, 2021). "Overall, these findings provide a mechanism that includes interactions among excess body fat, inflammation, metabolic dysfunction, and aromatase in the breast that help to explain why excess body fat is likely to increase the penetrance of breast cancer in BRCA1 and BRCA2 mutation carriers." (PMID 33649363, 2021). "With BRCA1 carriers being at high risk of developing this form of breast cancer, mDETECTTNBC may also play a role in the early detection of disease in this population." (PMID 34135468, 2021). "This is consistent with studies that showed PARPi(s) in combination with platinum-based drugs provide benefit not only to patients with germline BRCA1/2 mutations but also for breast cancers having molecular characteristics of BRCA1/2 mutant tumors or BRCAness." (PMID 34367977, 2021). "The BRCA1 mutation in breast cancer cells has been shown to significantly increase ROS levels in adjacent fibroblasts, thus leading to decreased Cav-1 expression and increased expression of monocarboxylate transporter 4 (MCT4), which is the main exporter of L-lactate from cells." (PMID 33498875, 2021). "Germ-line mutation in BRCA1 or BRCA2 are found in 3–4% of all women with breast cancer." (PMID 33996049, 2021). "In addition, ERα-positive BRCA1-associated breast cancer tends to develop in older ages (>50 years) and is less aggressive than ERα-negative, implying the association of ERα status and tumor progression in BRCA1-associated breast cancer." (PMID 33767581, 2021). "Interestingly, the treatment was shown to prevent contralateral breast cancer by 50% and demonstrated a 44% risk reduction of developing a second breast cancer in both BRCA1 and BRCA2 WT and mutant conditions." (PMID 35008272, 2021). "However, the lifetime risk of breast cancer is significantly higher in men with BRCA1 or BRCA2 mutation, with a incidence of 1.2% in men who carry a BRCA1 mutation and 6.8% in men who carry a BRCA2 mutation." (PMID 34711195, 2021). "Indeed, 13–18% of hereditary ovarian cancer cases, and around 5% of hereditary breast cancer cases are due to BRCA1 and BRCA2 mutations." (PMID 34242281, 2021). "Results of the current study based on this preclinical system suggest that patient-specific radiation therapy and AZD2281 concurrent treatment could be a useful strategy for controlling BRCA1-associated breast cancer." (PMID 33767581, 2021).
breast cancer (continued). "Carriers of germline pathogenic or likely pathogenic variants in BRCA1 or BRCA2 have significantly increased lifetime risks of breast cancer, ovarian cancer, and other cancer types; this phenomenon is known as hereditary breast and ovarian cancer (HBOC) syndrome." (PMID 35087763, 2021). "As morbidity increases, it has been recognized that genetic factors are associated with early-onset breast cancers, such as hereditary breast cancer and ovarian cancers, in which breast cancer susceptibility gene I (BRCA1) and breast cancer susceptibility gene II (BRCA2) play a role." (PMID 33492646, 2021). "Altogether, these findings suggest that DNp73 promotes BRCA1 deficient breast cancers." (PMID 34749806, 2021). "Previous studies indicate that acceptability of PND varies strongly, with a majority of breast cancer gene (BRCA1/2) mutation carriers finding it a too drastic measure to prevent HBOC, but couples with Huntington Disease overall finding PND acceptable, even if they had to terminate the pregnancy." (PMID 33611773, 2021). "In Haiti, 6.7% (5 of 75) of patients with breast cancer had a variant in BRCA1, BRCA2, or PALB2." (PMID 33646313, 2021). "Determining whether it is a biomarker of breast cancer susceptibility like BRCA1 and BACA2 is worth investigating." (PMID 34198652, 2021). "However, the current study showed 8.4% of metachronous contralateral breast cancer recurrence in patients with BRCA1/2 mutations." (PMID 34285295, 2021). "Women with HBOC syndrome, due to mutations in BRCA1/2 or other breast/ovarian cancer predisposition genes, are more likely to develop breast and ovarian cancer and are advised to have annual mammography tests for early detection of breast cancer." (PMID 34201956, 2021). "However, germline BRCA1/2 mutations only account for about 5–10% of breast cancer, limiting their broad applicability." (PMID 33520111, 2021). "Pre- or post-menopausal women with impairments in DNA repair due to germline BRCA1/2 mutations may be more suceptible to the pro-mutagenic and pro-proliferative effects of free estrogens, which could lead to increased breast cancer risk." (PMID 33649363, 2021). "The breast cancer susceptibility gene, BRCA1, can protect the cells under oxidative stress." (PMID 33754031, 2021). "Patients with BRCA1 mutations may develop basal-like subtypes or M type of triple-negative breast cancer besides metaplastic breast cancers." (PMID 33407746, 2021). "Preoperative diagnosis of BRCA1/2 mutation could impact surgical decision-making for breast cancer patients to undergo risk-reducing surgery at the time of initial surgery." (PMID 34285295, 2021). "The cumulative lifetime risk of breast cancer for BRCA1 carriers was 59.1% (95% CI: 44.1–73.6%): 64.4% (95% CI: 37.8–87.1%) in region 1 (~c.2281, BCCR), 43.4% (95% CI: 22.4–69.8%) in region 2 (c.2282 to c.4071, OCCR), and 67.3% (95% CI: 41.1–88.3%) in region 3 (c.4072~, BCCR)." (PMID 34063308, 2021). "Our results may support this latter study and suggest that there is a acumulative effect of ATM and BRCA1 mutations that increase the risk of breast cancer incidence." (PMID 34493284, 2021). "About 20% of HGSOCs harbor germline mutation in breast cancer genes BRCA1 or BRCA2." (PMID 34572778, 2021). "The observation of great intertumor heterogeneity among BRCA1-deficient mammary tumors propelled us to posit whether such phenomenon is ascribed to the intratumor heterogeneity among tumor cells." (PMID 34815798, 2021). "Mutations in the BRCA1 or BRCA2 genes induce the progress of breast cancer." (PMID 34710987, 2021). "PARP1/2 inhibitors (PARPis) are the first class of drugs acting by the principle of synthetic lethality that have been approved for clinical use for the treatment of homologous recombination (HR)-deficient types of cancer (mainly, BRCA1/2-deficient ovarian and breast cancers)." (PMID 34572428, 2021).
breast cancer (continued). "For carriers of pathogenic variants in BRCA1, the average cumulative risks by age 80 years is 72% (95% confidence interval 65–79%) for breast cancer and 44% (36–53%) for ovarian cancer, and the corresponding estimates for BRCA2 are 69% (61–77%) and 17% (11–25%) respectively." (PMID 33836815, 2021). "Indeed, DNA-damaging anticancer drugs, including cisplatin and AZD2281, have been used in the treatment of BRCA1-associated breast cancer." (PMID 33767581, 2021). "In conclusion, our findings demonstrate that preoperative identification of BRCA1/2 mutation could affect surgical decision-making for breast cancer patients in favor of contralateral RRM." (PMID 34285295, 2021). "In patients with a family history, current international accepted practice for breast cancer management is to address the risk based on expression of key genes; in those with BRCA1/2 abnormalities, the current advice is to encourage bilateral mastectomy at diagnosis." (PMID 33582622, 2021). "Moreover, the BRCA1/2 breast cancer mutation carriers with elevated cyclin E levels have a higher recurrence rate than those with low-cyclin E levels." (PMID 33916118, 2021). "The risk of breast cancer is elevated in men with a BRCA1 or BRCA2 mutation." (PMID 34461861, 2021). "Thus, these drugs have the potential to treat breast cancers deficient of damage repair pathway members such as BRCA1/2." (PMID 33805424, 2021). "In addition, we analyzed oncologic outcomes of BRCA1/2 mutation carriers with breast cancer according to types of surgery." (PMID 34285295, 2021). "A POLQ germline variant of unknown significance, as in the presented family, has already been reported in non-BRCA1/BRCA2-mutated breast cancer families." (PMID 34357098, 2021). "More studies are required to pinpoint whether the expression of ERBB2 plays a driver or passenger role in the BRCA1-deficient mouse mammary tumors." (PMID 34815798, 2021). "The disparity between the rate of development of effective therapies for other breast cancers and for those predisposed by BRCA1/2 mutation can likely be attributed to inability of physically inhibiting relevant target proteins, as is possible in other breast cancers." (PMID 34070674, 2021). "Additionally, 40 genes were associated with BRCA1-related breast cancers that had ChIP-seq data suggestive of enriched EZH2 binding." (PMID 34287743, 2021). "Potentially, denosumab may be used for the prophylactic treatment of breast cancer in BRCA1/2 genetically predisposed patients." (PMID 34770897, 2021). "Poly-ADP-polymerase (PARP) inhibitors have favorable therapeutic effects on BRCA1-mutated breast cancer, and preclinical studies have shown that the PARP inhibitor olaparib significantly reduced the proportion of BCSCs, suggesting that it acts against these cells." (PMID 33672204, 2021). "Further, we wondered whether different subtypes of BRCA1 deficient mammary tumors bear heterogeneous sensitivity to anti-cancer drugs." (PMID 34815798, 2021). "This individual was a distant relative of a family member in whom the pathogenic BRCA1 variant had first been identified and given her age at diagnosis of breast cancer, (an age common in women in the general population), could have represented a phenocopy." (PMID 33654310, 2021). "For example, the mutation of BRCA1, a tumor suppressor gene, could result in its dysfunction and elevate the risk of developing breast cancer at a certain age." (PMID 33644055, 2021). "The BRCA2 mutant case and the four other cases showing HRD-like SNV and indel patterns also showed the presence of the rearrangement signatures associated with BRCA1/2 deficiency, although to a lesser extent than that seen in TCGA-64-1680 and in BRCA1/2 mutant breast cancer in general." (PMID 34145376, 2021).
breast cancer (continued). "It is poorly understood, though, how this process might be affected by deletions or mutations in the breast cancer type 1 susceptibility (BRCA1) gene in patients with a lifetime risk of developing breast and/or ovarian cancer." (PMID 33513753, 2021). "In addition, a few recently published studies provided more information about the inter- and intra-heterogeneity of BRCA1-deficient mammary tumors/breast cancers." (PMID 34815798, 2021). "BRCA genes are essential DNA double-strand break (DSB) repair, while the mutations in the genes can lead to a predisposition to cancers, including breast cancer and ovarian cancer, with the risk of breast cancer and contralateral breast cancer both increased by BRCA1 and BRCA2 mutations." (PMID 34376160, 2021). "However, the potential impact of BRCA1/2 mutations on the individual cell populations within the unique tumor microenvironment and their relation to breast cancer has been understudied." (PMID 33540843, 2021). "Taken together, the BRCA1 deficient mammary tumors could be classified into four distinct subtypes, with respective markers genes, molecular features and anti-cancer drug sensitivities." (PMID 34815798, 2021). "The reason for this observation is unclear, however BRCA2 gene mutation carriers are at a reduced overall breast cancer risk than BRCA1 gene mutation carriers (both alone and in combination with high MD), as shown in data generated from the Tyrer-Cuzik risk assessment calculator." (PMID 34209669, 2021). "Furthermore, in another study, it was showed that deleterious BRCA1 mutations were detected in 37% (6/16) of patients selected from high-risk breast cancer families." (PMID 33726785, 2021). "To understand the mechanism underlying the delayed mammary tumor development in B1P2p mice, we asked whether combined loss of BRCA1 and PALB2 would cause synthetic lethality in MECs, thereby reducing their overall tumorigenic potential." (PMID 33893322, 2021). "The link between BRCA1/2 mutations and high susceptibility to breast cancer is well established." (PMID 35008272, 2021). "Heterozygous BRCA1 mutations in mammary tissue microenvironment might create a pro-tumorigenic niche, which may significantly contribute to breast cancer development in carriers of germline BRCA1 mutations." (PMID 35008272, 2021). "In addition to ovarian and breast cancers, loss-of-function mutations in BRCA1 and BRCA2 genes are also linked to an increased risk of pancreatic cancer, with ~ 4 to 7% of pancreatic cancer patients harboring germline BRCA mutations." (PMID 33407459, 2021). "Through these means, we sought to examine the effect of stiffness on RASSF1A expression in the context of MD and in BRCA WT versus mutant backgrounds in order to better understand the combinatory contribution of high MD and BRCA1/2 gene mutations to breast cancer risk." (PMID 34209669, 2021). "Unilateral breast cancer (UBC) patients with germline pathogenic BRCA1/2 variants have a higher risk of developing contralateral breast cancer (CBC) and need contralateral risk-reducing local treatments, including contralateral risk-reducing mastectomy (CRRM) and prophylactic irradiation (CPI)." (PMID 34563200, 2021). "Examples include hypermethylation of the BRCA1 promoter region, which was found to be associated with increased risk of early onset breast cancer, and tumours from cases showing blood hypermethylation appear to have similar pathological features as BRCA1 mutated tumours." (PMID 34943892, 2021). "The largest risk difference was seen for women with a first breast cancer diagnosis before the age of 40, with BRCA1 heterozygotes at the 5th percentile of the ER-negative PRS313 having a 10- and 20-year risk of 22% and 35% compared with 32% and 49% at the 95th percentile, respectively." (PMID 34113011, 2021).